Y_RNA (Y RNA )
Gene: Miscellaneous RNA gene on chromosome 7 (103,433,461 to 103,433,561, reverse strand). Ensembl gene ENSG00000251852.
Homologues: Orthologues: chimpanzee Y_RNA (99% identical), macaque Y_RNA (97% identical), guinea pig Y_RNA (92% identical). Paralogues in human: Y_RNA (92% identical), Y_RNA (90% identical), Y_RNA (89% identical), RNY3 (88% identical), Y_RNA (88% identical), Y_RNA (87% identical), RNY3P1 (86% identical), Y_RNA (86% identical), Y_RNA (85% identical), RNY3P2 (84% identical), Y_RNA (84% identical), RNY3P16 (83% identical), and 97 more.